GSK3B (glycogen synthase kinase 3 beta)
Diseases named in the same sentence as GSK3B in open-access papers (continued):
Sharing a sentence is not in itself a finding about the gene and the disease.
liver failure (4 papers, 2012 to 2023). A liver disease characterized by the liver losing or has lost all of its function. "Deeply, we also explored how inhibition of GSK3β ameliorates hepatocyte death while potential protein mechanisms are involved, providing new directions for the treatment of liver failure." (PMID 37443080, 2023). "More researchers are attaching great importance to GSK-3β as a target for the treatment of liver failure, neurodegenerative diseases, and other diseases." (PMID 26770978, 2015). "For this reason, we hypothesized whether GSK3β inhibitors could serve a hepatoprotective function and improve hepatic failure by inhibiting multiple modes of cell death in ALF." (PMID 37443080, 2023). "Thus, the GSK3β activation, as measured by dephosphoryaltion at serine-9, is triggered in the early phase of the D-GalN/LPS induced liver failure." (PMID 23028846, 2012). "Therefore, GSK3β inhibition was capable of inhibiting hepatocyte apoptosis in hepatic failure induced by D-GalN/LPS." (PMID 23028846, 2012). "To dissect the role of GSK3β in the pathogenesis of liver failure, we first determined in vivo whether the GSK3β phosphorylation/dephosphorylation is triggered in acute liver injury." (PMID 23028846, 2012). "Thus, inhibition of GSK3β activity suppressed expression of pro-inflammatory cytokine, and reduced neutrophil activation in D-GalN/LPS induced liver failure." (PMID 23028846, 2012). "As total GSK3β levels were unchanged among the different time points, our result indicates that the liver GSK3β activity, rather than its protein, was increased during early phase of liver failure induced by D-GalN/LPS, but declined to the basal state thereafter." (PMID 23028846, 2012). "To address the functional significance of GSK3β in liver injury, we treated mice with a GSK3β specific chemical inhibitor, SB216763, 2 hours prior to or after the onset of liver failure." (PMID 23028846, 2012). "To address the effect of inhibiting activity of GSK3β on hepatic injury, we investigated whether SB216763 regulates serum AST and ALT levels in D-GalN/LPS-induced liver failure." (PMID 23028846, 2012).
medullary thyroid cancer (4 papers, 2010 to 2019). "From the medical point of view, inactivation of GSK-3β by LiCl alone or in combination with HDACi was found to be sufficient to inhibit growth in medullary thyroid cancer cells." (PMID 21814573, 2011). "GSK-3β activation was necessary for proliferation and survival in colorectal cancer cells, ovarian cancer cells and medullary thyroid cancer cells." (PMID 20704706, 2010).
memory (4 papers, 2013 to 2025). The activities involved in the mental information processing system that receives (registers), modifies, stores, and retrieves informational stimuli. "The decreased oxidative stress due to elevation of Nrf2 by these agents may be playing essential role in protection against PP2A/GSK3β changes and finally decreased Tau phosphorylation and deposition in OKA induced memory impaired rats." (PMID 24078822, 2013).
meningioma (4 papers, 2022 to 2024). A generally slow growing tumor attached to the dura mater. "For example, in both hepatocellular carcinoma and meningioma Gal-3 activates the PI3K-Akt-GSK-3β-β-catenin signaling cascade by enhancing GSK-3β phosphorylation via the activation of the PI3K-Akt signaling pathway." (PMID 38022609, 2023). "GSK-3β inhibition has shown promising results in the treatment of multiple malignancies, and is now being investigated for several refractory neoplasms, including meningiomas." (PMID 36672431, 2023). "Zerumbone enhances GSK3β phosphorylation in meningioma cells." (PMID 36558562, 2022).
non-alcoholic steatohepatitis (4 papers, 2020 to 2025). "For instance, miR-29a via modulating the GSK-3β/SIRT1 could ameliorate mouse non-alcoholic steatohepatitis." (PMID 37441551, 2023).
parasite infection (4 papers, 2018 to 2024). "Since GSK3β is involved in the innate and adaptive immune response through the regulation of cytokine production, higher GSK3β in the liver of untreated NK65-infected mice may be associated with increased pro-inflammatory cytokine production during inflammation upon parasite infection." (PMID 33803419, 2021). "GSK3B, as a central regulator of inflammatory response, play roles in immune system against viral, fungal and parasitic infections." (PMID 30687082, 2018). "Moreover, Hs GSK-3β was reported to modulate the inflammatory response activated by parasite infections, marked by a dramatic increase in cytokine production." (PMID 35408690, 2022).
psoriasis (4 papers, 2021 to 2025). An autoimmune condition characterized by red, well-delineated plaques with silvery scales that are usually on the extensor surfaces and scalp. "The activation of the GSK3β signaling pathway may have a positive role in promoting epidermal differentiate in psoriasis." (PMID 35008494, 2021). "Regarding the candidate targets, estrogen receptor (ESR1) showed the highest degree (113°), followed by PTGS2 (86°), NOS2 (81°), PPARG (60°), and GSK3B (56°), which demonstrated the potential therapeutic effect of each drug in LXJD formula for ameliorating psoriasis." (PMID 34168554, 2021).
small cell lung carcinoma (4 papers, 2017 to 2024). Small cell lung cancer (SCLC) is a highly aggressive malignant neoplasm, accounting for 10-15% of lung cancer cases, characterized byrapid growth, and early metastasis. "Recent studies in small cell lung cancer (SCLC) revealed that LINC01089 knockdown mediated changes in the expression of N-cadherin, E-cadherin, Snail, Slug, and SRPR1 in A549 and H1299 cells, with protein levels of p-GSK-3β and β-catenin also increased following siLINC01089 transfection." (PMID 39334363, 2024).
status epilepticus (4 papers, 2018 to 2022). Status epilepticus is defined as a continuous seizure lasting more than 30 min, or two or more seizures without full recovery of consciousness between any of them. "In line with this, we have previously shown that there are subfield-specific differences in GSK-3β activity following intraamygdala KA-induced status epilepticus." (PMID 31780921, 2019). "Consistent with this, overexpression of GSK-3β exacerbated status epilepticus-induced neurodegeneration in mice." (PMID 30237424, 2018). "Surprisingly, decreasing GSK-3 activity, either via overexpression of GSK-3β-DN or through the use of specific GSK-3 inhibitors, also exacerbated hippocampal damage and increased seizure severity during status epilepticus." (PMID 30237424, 2018).
temporal lobe epilepsy (4 papers, 2017 to 2023). A localization-related (focal) form of epilepsy characterized by recurrent seizures that arise from foci within the temporal lobe, most commonly from its mesial aspect. "Recently, the PI3K/Akt/GSK3β/eIF2α/ATF4 pathway was shown to be responsible for increased xCT expression in the hippocampus of patients suffering from temporal lobe epilepsy." (PMID 28086920, 2017). "Similarly, CDK5 and GSK-3β were both reported to be overactivated in temporal lobe epilepsy." (PMID 33681188, 2020).
Ureteral obstruction (4 papers, 2012 to 2026). Obstruction of the flow of urine through the ureter. "In experimental kidney diseases, Snail-1 is overexpressed in renal tubular cells in the unilateral ureteral obstruction model, and its expression is posttranscriptionally stabilized by glycogen synthase kinase 3 β (GSK3β)." (PMID 22028950, 2012).
amnesia (3 papers, 2008 to 2023). Pathologic partial or complete loss of the ability to recall past experiences ( AMNESIA, RETROGRADE) or to form new memories ( AMNESIA, ANTEROGRADE). "Since ZIP induces catastrophic and irreversible amnesia, it is likely that GSK-3β activation induces a persistent change of memory-storing synapses (i.e., changes in synaptic structures, synaptic loss etc.)." (PMID 33106552, 2020). "Moreover, the observed effects clearly demonstrated that E169 mitigated the disturbance in the PI3K/AKT/GSK-3β signaling pathway through its selective H3R antagonistic effect, therefore balancing the disturbed phosphorylation of GSK-3β caused following amnesia induced by MK801." (PMID 37628900, 2023). "Therefore, retrograde amnesia related to GSK-3β inhibition could be due to an impairment of memory reconsolidation, not to facilitation of extinction." (PMID 18958152, 2008). "Therefore, it is possible that GSK-3β inhibition-induced retrograde amnesia may be due to facilitation of extinction or impairment of reconsolidation." (PMID 18958152, 2008).
atrial fibrillation (3 papers, 2020 to 2024). A disorder characterized by an electrocardiographic finding of a supraventricular arrhythmia characterized by the replacement of consistent P waves by rapid oscillations or fibrillatory waves that vary in size, shape and timing and are accompanied by an irregular ventricular response. "The minor allele G of the intron variant GSK-3β rs796944992 was observed to increase the risk of atrial fibrillation." (PMID 36979891, 2023). "The mechanism by which GSK-3β mediates atrial fibrillation through the oxidative stress pathway can be further explored in future studies." (PMID 36979891, 2023). "MiR-26 can also suppress atrial fibrillation (AF) and cardiomyocyte hypertrophy by targeting β-MHC, GSK3β, GATA4, KCNJ2, and PLCβ1." (PMID 38195542, 2024).
attention deficit-hyperactivity disorder (3 papers, 2017 to 2024). A disorder characterized by a marked pattern of inattention and/or hyperactivity-impulsivity that is inconsistent with developmental level and clearly interferes with functioning in at least two settings (e.g. at home and at school). "In harmony with our findings, others have demonstrated that thymol reduced the GSK-3β protein expression in an experimental model of monosodium glutamate-induced attention deficit hyperactivity disorder." (PMID 39204199, 2024). "Due to the nonspecific alterations of the dopaminergic system in the GSK-3β over-expressing mice, which are also recognizable in other psychiatric disorders, such as schizophrenia and attention-deficit hyperactivity disorder (ADHD), this animal model, however, lacks specificity for mania." (PMID 29027157, 2017).
autoimmune disease (3 papers, 2015 to 2023). A disorder resulting from loss of function or tissue destruction of an organ or multiple organs, arising from humoral or cellular immune responses of the individual to their own tissue constituents. "On the other hand, GSK3β has been implicated in Sjögren's syndrome, an autoimmune disease associated with IFI16 overexpression and autoantibodies against IFI16 filaments." (PMID 37283074, 2023).
Brain atrophy (3 papers, 2022 to 2025). Partial or complete wasting (loss) of brain tissue that was once present. "It is important that both mouse models were characterized by brain atrophy, showing that the GSK3β-CUGBP1 pathway plays a critical role in the development of brain atrophy in DM1." (PMID 37445828, 2023). "Although more pre-clinical work is needed to determine whether the inhibitors of GSK3 reduce brain atrophy in homozygous DMSXL mice, this study shows that the correction of CUGBP1 activity via GSK3β signaling is a critical target in DM1 therapy." (PMID 37445828, 2023).
chronic allograft nephropathy (3 papers, 2012 to 2024). "Furthermore, CXCR4 induces epithelial-mesenchymal transition (EMT) through activation of the Wnt/β-catenin signaling pathway in rat chronic allograft nephropathy, consistent with another report suggesting CXCR4 involvement in the JAK/STAT/GSK3β/β-catenin pathway activation in the UUO model." (PMID 39684834, 2024).
chronic obstructive pulmonary disease (3 papers, 2012 to 2021). A chronic and progressive lung disorder characterized by the loss of elasticity of the bronchial tree and the air sacs, destruction of the air sacs wall, thickening of the bronchial wall, and mucous accumulation in the bronchial tree. "It has been revealed that glycyrrhizic acid could alleviate inflammatory lung disease, including chronic obstructive pulmonary disease by promoting the downstream PI3K/Akt/GSK3β signaling pathway." (PMID 34250093, 2021). "Such an induction of FMT-related processes by synergic activation of TGF-β/GSK-3β signaling was previously seen in mouse mesenchymal C3H10T1/2 cells, mouse embryonic fibroblasts, and pulmonary fibroblasts from individuals with chronic obstructive pulmonary disease." (PMID 22988467, 2012).
colorectal adenocarcinoma (3 papers, 2012 to 2023). The most common type of colorectal carcinoma. "We searched the TCGA database for the presence of altered APC, β-Catenin (CTNNB1) and GSK3β in 526 colorectal adenocarcinoma patient samples (TCGA, PanCancer Atlas)." (PMID 35625868, 2022). "To understand the relevance of the observed connection between NLRP12 and β-catenin in human CRC, we measured the expression of NLRP12, β-catenin, and p-GSK3β in human colorectal adenocarcinoma and adjacent nontumor tissue." (PMID 37581937, 2023).
coronary artery disease (3 papers, 2021 to 2025). "Similarly, activity-suppressing phosphorylation of SERCA2A at serine 663 by glycogen synthase kinase 3 beta (GSK3β) reduces SERCA2 activity, leading to decreased Ca2+ uptake, cytosolic and mitochondrial Ca2+ overload, and increased cell death in ischemic heart disease and reperfusion injury." (PMID 40653168, 2025).
dengue disease (3 papers, 2014 to 2022). Dengue fever (DF), caused by dengue virus, is an arboviral disease characterized by an initial non-specific febrile illness that can sometimes progress to more severe forms manifesting capillary leakage and hemorrhage (dengue hemorrhagic fever, or DHF) and shock (dengue shock syndrome, or DSS). "The role of GSK3β in the development of the Denguedisease and the immune-pathogenic mechanisms responsible for severe Dengue fever hasbeen described." (PMID 32130369, 2020). "In this work, the role of the protein GSK3β during Dengue virus infection wasinvestigated in Huh7 and Vero cells." (PMID 32130369, 2020). "With respect to a possible pathogenic role for aberrant IL-10 production in DHF/DSS patients, targeting the Syk/PKA/PI3K/PKB/GSK-3β/CREB signaling axis may represent a viable therapeutic strategy for combating the progression of severe dengue diseases." (PMID 25412261, 2014). "Since there is no vaccine or drugs currently available for thetreatment of Dengue fever, GSK3B inhibition could counteract or reduce complicationsfrom the disease." (PMID 32130369, 2020).
Down syndrome (3 papers, 2015 to 2025). "Like lithium, fluoxetine or selective 5-HT1A agonist 8OH-DPAT induces the phosphorylation of GSK3β in mouse and human Down’s syndrome neural precursor cells in vitro." (PMID 37958600, 2023). "In neurocognitive disorders such as Down syndrome and Fragile X where neurogenesis is impaired, administration of GSK3β inhibitors were shown to enhance neurogenesis." (PMID 26157370, 2015). "Multiple studies have shown that inhibitors of GSK3β may be able to help normalize abnormal levels of both LTP and LDP in the brain, as treatment with GSK3β inhibitors was accompanied by increased cognitive abilities in mouse models with Fragile X syndrome, and Down syndrome, and AD." (PMID 39996845, 2025).
endometriosis (3 papers, 2019 to 2024). The growth of functional endometrial tissue in anatomic sites outside the uterine body. "For example, the aberrant activation of Wnt/β-catenin signaling during the secretory phase of the menstrual cycle in endometriosis has been associated with excessive inactivation of GSK3β." (PMID 39125716, 2024). "We also found that Nodal expression was posttranslationally regulated through alteration in GSK-3β activity in endometriosis-OCCCa lesions." (PMID 30943930, 2019). "Nodal expression was significantly higher in endometriosis and OCCCa lesions as compared to that of non-OCCCas, with positive correlations to phosphorylated forms of both Smad2 (pSmad2) and GSK-3β." (PMID 30943930, 2019). "Given our previous data showing that TGF-β signaling leads to functional inhibition of GSK-3β activity through pAkt activation, it appears that Nodal expression may be regulated by both Smad- and non-Smad-dependent pathways in response to TGF-β action in the endometriosis-OCCCa lesions." (PMID 30943930, 2019).
gallbladder cancer (3 papers, 2017 to 2023).
hepatoblastoma (3 papers, 2016 to 2023). Hepatoblastoma (HB) is a malignant hepatic tumor and is the most common pediatric liver cancer. "In hepatoblastoma cell lines, GSK3β inhibition by pharmacological or gene knockdown/mutant techniques limited anti-cancer drug induced apoptosis." (PMID 27195613, 2016). "A recent study demonstrated that miR-624-5p regulates Wnt signaling in hepatoblastoma; thus, we speculated that GSK-3β might be a target of miR-624-5p." (PMID 35581180, 2022).
Hypercholesterolemia (3 papers, 2013 to 2016). An increased concentration of cholesterol in the blood. "Sevoflurane and ischemic postconditioning significantly increased the p-GSK3β in healthy rats (P < 0.01), however, this effect was blocked by hypercholesterolemia." (PMID 24124583, 2013). "Hypercholesterolemia blocked the ability of sevoflurane to phosphorylate components of RISK pathway and consequently, the phosphorylation of the downstream target GSK3β." (PMID 24124583, 2013).
ischemia reperfusion injury (3 papers, 2010 to 2022). Adverse functional, metabolic, or structural changes in ischemic tissues resulting from the restoration of blood flow to the tissue (reperfusion), including swelling; hemorrhage; necrosis; and damage from free radicals. "In this study, the significant changes in the expression of HIF-1α, p-AkT and p-GSK-3β/GSK-3β ratio in the heart homogenates of ischemia-reperfusion injury subjected rats were also observed." (PMID 36542041, 2022). "Phosphorylation of GSK3β can interact with ANT to weaken the formation of ANT-CypD complex, thereby inhibiting the opening of mPTP and reducing myocardial cell apoptosis after ischemia-reperfusion injury." (PMID 35383148, 2022).
liver inflammation (3 papers, 2019 to 2024). "In the current study, phosphorylation of GSK-3β was attenuated upon BA sludge, which led to the activation of GSK-3β, promoting the activation and migration of HSCs and exacerbating the development of liver inflammation and fibrosis." (PMID 38808258, 2024). "Moreover, CH4 enhanced GSK-3β activation, thus leading to an increased expression of the anti-inflammatory cytokine IL-10, similar to the findings for a carbon tetrachloride–derived liver inflammation model." (PMID 31807906, 2019). "Disruption of macrophage PTEN activates PI3K/Akt, inactivates GSK3β, activates NICD/NRF2, and ultimately inhibits STING-TBK1 signaling, reducing APAP-induced liver inflammation." (PMID 37370115, 2023).
mantle cell lymphoma (3 papers, 2020 to 2023). Mantle cell lymphoma is a rare form of malignant non-Hodgkin lymphoma affecting B lymphocytes in the lymph nodes in a region called the ``mantle zone''. "mTOR directly mediates Cyclin D1 downregulation through glycogen synthase kinase (GSK)-3b in mantle cell lymphoma (MCL)." (PMID 33489922, 2020). "It has been found that Deferasirox (DFX) can trigger the proteolysis of cyclin D1 in mantle cell lymphoma (MCL), which requires the participation of GSK-3β." (PMID 36829936, 2023).